VIM (vimentin)
Diseases named in the same sentence as VIM in open-access papers (continued):
Sharing a sentence is not in itself a finding about the gene and the disease.
osteosarcoma (73 papers, 2006 to 2025). A usually aggressive malignant bone-forming mesenchymal neoplasm, predominantly affecting adolescents and young adults. "Decitabine exposure in osteosarcoma reduces the protein expression of the metastasis-associated markers VIMENTIN, SLUG, ZEB1, and MMP9, with a concurrent decrease in mRNA expression of the known stem cell markers SOX2, OCT4, and NANOG." (PMID 37197432, 2023). "Overexpression of FAM83H increased the migration and invasion activity of osteosarcoma cells, which was associated with increased expression of vimentin and snail." (PMID 31215499, 2019). "Furthermore, immunofluorescent colabeling of SOX9 and vimentin—two hallmark markers of osteosarcoma—confirmed that the PDOs preserved key molecular characteristics of their parental tumors." (PMID 41382267, 2025). "Possible clinical applications of vimentin as a diagnostic tool in immunohistochemistry include the use of a combination of alkaline phosphatase staining with vimentin staining of lytic bone lesions in differentiating canine osteosarcoma from other bone neoplasms." (PMID 40507962, 2025). "Transitional zones between these components were present, with morphology and immunoprofile (vimentin-positive, CK-negative) supporting osteosarcoma." (PMID 41357596, 2025). "Our results demonstrated a drop in the expression levels of N-cadherin and Vimentin, whereas there was an upregulation of E-cadherin, indicating that osteosarcoma cell invasion, migration, and proliferation are hampered by DUSP3 overexpression." (PMID 39744427, 2025). "Activation of TGF-β in osteosarcoma cells leads to decreased expression of E-cadherin and increased expression of mesenchymal markers such as N-cadherin and vimentin, thereby enhancing invasive and metastatic capabilities." (PMID 40075892, 2025). "The results of WB analysis showed that overexpressed HSPD1 suppressed the expression of E-cadherin, and enhanced the expression of N-cadherin and vimentin in osteosarcoma cells." (PMID 39430254, 2024). "In this study, Western blot confirmed that knockdown of HSPD1 in osteosarcoma cells triggered a decrease in Vimentin and N-cadherin and an upregulation of E-cadherin." (PMID 39430254, 2024). "MK2206 treatment significantly reduced the levels of p-AKT, p-mTOR, N-cadherin, and vimentin in osteosarcoma cells, while overexpression of HSPD1 partially abrogated these inhibitory effects." (PMID 39430254, 2024). "In osteosarcoma, PKIB was linked to the expression of two well-known epithelial–mesenchymal transition proteins, E-cadherin and vimentin." (PMID 38731883, 2024). "In osteosarcoma, the expression of E-cadherin and vimentin was changed by induced overexpression of PKIB." (PMID 38731883, 2024). "The EMT markers N-cadherin, vimentin and proto-oncogene c-Myc in osteosarcoma cells were significantly downregulated with BTFPTU treatment." (PMID 38216937, 2024). "In Han’s study, Raman bands at 1000, 1075, and 1375 cm−1 (CD63, vimentin (VIM), and epithelial cell adhesion molecule (EpCAM)) in exosomes of osteosarcoma patients were significantly higher." (PMID 36814817, 2023). "Bone is the only connective tissue producing ALPL in dogs and it can therefore be used to differentiate the canine osteosarcoma from other vimentin-positive tumors." (PMID 37048099, 2023). "Overexpression of LINC01410 induced N-cadherin and vimentin expression while inhibiting E-cadherin expression in osteosarcoma cells." (PMID 36326314, 2022). "The overexpression of vimentin and ezrin genes was associated with epithelial-mesenchymal transition (EMT), a key process in metastasis and progression in osteosarcoma (OS)." (PMID 35625426, 2022). "In the present study, overexpression of STAT3 enhanced the migration and invasion of osteosarcoma cells by increasing the expression of N-cadherin, Vimentin, Snail and reducing the expression of E-cadherin to subsequently promote the EMT process." (PMID 33546665, 2021).
osteosarcoma (continued). "BYSL overexpression decreased epithelial marker (E-cadherin) and increased mesenchymal marker (N-cadherin and Vimentin) of osteosarcoma cells in hypoxia." (PMID 35154253, 2021). "During the EMT of osteosarcoma, E-cadherin expression is repressed, whereas the expression of N-cadherin, Vimentin and Snail is significantly upregulated." (PMID 33546665, 2021). "Immunofluorescence assays revealed that after silencing MELTF-AS1 in osteosarcoma cells, the protein level of Vimentin decreased and the protein level of E-cadherin increased." (PMID 34729248, 2021). "FHIT overexpression decreased the mRNA and protein expression of Ki67, N-cadherin, and vimentin but increased expression of E-cadherin in osteosarcoma cells." (PMID 34368151, 2021). "The circPIP5K1A knockdown increased E-Cadherin expression and decreased Vimentin expression in osteosarcoma cells." (PMID 34774083, 2021). "Overexpression of LINC01410 induced N-cadherin and Vimentin expression and inhibited E-cadherin expression in osteosarcoma cells." (PMID 33401246, 2020). "To determine vimentin expression after knocking down PLOD1 in osteosarcoma cells, we performed immunofluorescence (IF) staining, and the results also confirmed previous results using WB." (PMID 33134376, 2020). "Altogether, our results support that exosomes secreted by ADSCs in adipose tissues can activate the expression of COLGALT2 in osteosarcoma cells, which fosters cancer metastasis and growth by increasing vimentin and MMP expression." (PMID 32523950, 2020). "The decrease of vimentin expression also indicated that AFAP1-AS1 knockdown suppressed osteosarcoma invasiveness capability." (PMID 31443665, 2019). "The upregulation of vimentin and N-cadherin (mesenchymal markers) expression and the downregulation of E-cadherin (epithelial marker) enhance the ability of osteosarcoma cells to migrate and invade." (PMID 30235848, 2018). "The results showed the notably decreased level of N-cadherin, Vimentin, and Snail, but remarkably increased level of E-cadherin after the osteosarcoma cells (both MG63 and U2OS cell lines) were treated with miR-1284 mimics." (PMID 29899164, 2018). "Ectopic expression of CCAT2 promoted osteosarcoma cell invasion and increased the expression of mesenchymal markers N‐cadherin, vimentin and snail mRNA and decreased the expression of N‐cadherin marker E‐cadherin." (PMID 29502343, 2018). "TRIM14 knockdown suppressed the migration and invasion ability of osteosarcoma cells, and induced downregulation of cyclin D1 and vimentin and simultaneous upregulation of E-cadherin." (PMID 28205534, 2017). "All CMSs expressed vimentin, and higher levels of vimentin expression were noted in fibrosarcomas and osteosarcomas." (PMID 24321325, 2013). "The osteosarcoma component showed diffuse vimentin expression and focal S-100 reactivity." (PMID 41357596, 2025). "Similarly to humans, overexpression of vimentin in canine osteosarcoma is thought to contribute to enhanced tumor cell motility, invasiveness, and a more aggressive clinical behavior." (PMID 40507962, 2025). "Overexpressing PKIB in osteosarcoma cells downregulated E-cadherin but upregulated vimentin." (PMID 38731883, 2024). "Staining for vimentin has been reported in osteosarcomas, fibrosarcomas, and carcinosarcomas." (PMID 39420880, 2024). "Thus, presence of vimentin combined with ALPL confirmed osteosarcoma origin of the isolated COS cells." (PMID 37048099, 2023). "Sections were co-stained for vimentin to distinguish osteosarcoma cells from lung parenchyma." (PMID 37106386, 2023).
osteosarcoma (continued). "In addition, PKIB promoted the proliferation of osteosarcoma cells probably through affecting phosphorylation level of Akt and inhibited the migration and invasion of osteosarcoma cells through affecting the expression of E-cad and VIM." (PMID 36072791, 2022). "The results showed that PKIB significantly inhibited the migration and invasion of osteosarcoma cells, and the Western blot experiments showed that the protein level of E-cad was upregulated and of VIM was downregulated in 143-B cell recombinant expression PKIB." (PMID 36072791, 2022). "EMT is characterized by a complex dynamic change, with a concomitant decline of epithelial cell markers (including β-catenin and E-cadherin) and increased mesenchymal markers (including vimentin and N-cadherin), which has been shown to contribute to cancer metastasis and invasion in osteosarcoma." (PMID 35154253, 2021). "Although this finding still requires further investigation, we hypothesize that ADSC-secreted exosomes can induce COLGALT2 expression in osteosarcoma cells, accompanied by the downstream activation of vimentin and MMP2/9." (PMID 32523950, 2020). "To identify the potential downstream target genes related to lincFOXF1 in osteosarcoma, we conducted qRT‐PCR to assess expression of multiple molecules (such as N‐cadherin, Integrin, CD44, ICAM‐1, Vimentin, Fibronectin, GIT1 and FOXF1) in osteosarcoma cells after gain or loss of lincFOXF1 function." (PMID 32945076, 2020). "In addition, western blot results showed that silenced WTAP evidently repressed the expression of mesenchymal markers (cadherin and vimentin) and induced the expression of epithelial marker E-cadherin which was attenuated by shHMBOX1 in osteosarcoma cells." (PMID 32814762, 2020). "In addition, higher expression of COLGALT2 was found to be associated with higher levels of vimentin and MMP2/9 in osteosarcoma cells." (PMID 32523950, 2020). "In addition, FAM83H-related proliferation and invasiveness of osteosarcoma cells were related to the expression of β-catenin, cyclin D1, p27, snail, and vimentin." (PMID 31215499, 2019). "Since our present findings associate cytoplasmic p27 localization with the metastatic potential of osteosarcoma cells, we evaluated the mRNA levels of the set of metastatic markers, VIM, SNA2, CDH2, CTNNB1 and STMN1 following XPO1 inhibition and AZD1775 exposure, by RT-qPCR." (PMID 30992462, 2019). "Being a tumour of mesenchymal origin, osteosarcoma shows positivity to vimentin." (PMID 29609578, 2018). "In a dose- and time-dependent manner, MTF inhibited proliferation, migration and invasion of osteosarcoma cells and this effect was associated with decreased expression of phosphorylated AKT serine/threonine kinase 1 (p-Akt) and vimentin (VIM), and increased expression of PTEN and cadherin 1 (CDH1)." (PMID 30241339, 2018). "Jiuet al. showed recently that transverse arcs, which are actin bundles containing the motor protein myosin II, are essential for the retrograde flow of small vimentin particles and their incorporation into perinuclear vimentin filaments in the osteosarcoma U2OS cells." (PMID 30505430, 2018). "Notably, inhibition of AKT expression by siRNA suppressed cyclin D1 and vimentin levels and increased E-cadherin expression in osteosarcoma cells." (PMID 28205534, 2017). "Furthermore, high level of miR-429 in osteosarcoma cells obviously increased the expression of E-cadherin protein but decreased the expression of Vimentin, N-Cadherin and Snail proteins." (PMID 28694763, 2017). "In both human and canine osteosarcoma, elevated vimentin expression reflects the tumor’s mesenchymal origin and may further contribute to enhanced migratory and invasive behavior through EMT-like processes, underscoring its potential role in disease progression and metastasis." (PMID 40507962, 2025).
osteosarcoma (continued). "Consequently, patients with osteosarcoma characterized by EMT often face poorer treatment outcomes, as the presence of mesenchymal markers like N-cadherin and vimentin has been associated with lower overall survival rates and higher recurrence following chemotherapy." (PMID 40075892, 2025). "STP could specifically bind to cell surface vimentin in osteosarcoma, but does not bind to cell surface vimentin–deficient hFOB1.19 cells and blood cells." (PMID 34776965, 2021). "A similar mechanism was observed in osteosarcoma, where KEAP1-259aa interacts with cytoplasmic Vimentin to regulate cell stemness, with Vimentin-induced multinucleation also affecting tumor cell stemness." (PMID 40307891, 2025). "Western blot analysis showed increased protein expression levels of N-cadherin and Vimentin and a decreased level of E-cadherin; thus suggesting that the downregulation of RILP significantly promotes the metastatic ability of osteosarcoma cells." (PMID 37789274, 2023). "In osteosarcoma, COX-2 affects the expression levels of vimentin, E-cadherin, MMP-9 and MMP-2 by activating the PI3K/AKT/NF-κ b signaling pathway, leading to a significant increase in the migratory ability of osteosarcoma cells." (PMID 37404761, 2023). "Subsequently, HSP90 knockdown can lead to the reduced osteosarcoma cells viability and migration and the dramatically reduced protein levels of p-AKT1, AKT1, Vimentin, as well as ki-67." (PMID 37861934, 2023). "Competitive binding of lnc-SELPLG-2:1 to hsa-hsa-miR-10a-5p prevented BTRC from miRNA-mediated degradation, thereby activating the expression of VIM, MMP9, and MMP2, promoting osteosarcoma cell proliferation, migration, and invasion, and inhibiting apoptosis." (PMID 36199080, 2022). "The expression of mesenchymal marker Vimentin and the matrix metalloproteinase 2 (MMP-2) which degrades and remodels the extracellular matrix (ECM) was increased in most of the osteosarcoma cell lines." (PMID 36344502, 2022). "Mechanistically, FHIT overexpression repressed N-cadherin, vimentin, and Ki67 and increased the expression of E-cadherin, suggesting that its overexpression inhibits EMT in osteosarcoma cells." (PMID 34368151, 2021). "Then, in osteosarcoma cells, we evaluated COLGALT2, vimentin and matrix metalloproteinase 2/9 (MMP2/9) expression together with ADSC exosomes using qRT-PCR and western blotting." (PMID 32523950, 2020). "In osteosarcoma cells, stimulation of P2X7R reduced the expression of E-cadherin, and induced the expression of Snail, vimentin and fibronectin." (PMID 32825056, 2020). "To understand the role of COLGALT2 in the osteosarcoma-promoting effect of ADSC exosomes, we first examined COLGALT2 and vimentin expression in exosome-treated osteosarcoma cells by immunofluorescence." (PMID 32523950, 2020). "Exosome treatment markedly increased COLGALT2, vimentin and MMP2/9 expression in the osteosarcoma cells." (PMID 32523950, 2020). "In support of this finding, osteosarcoma cells expressing KIFs but lacking VIFs exert increased traction forces compared to these cells when vimentin is expressed." (PMID 36200046, 2022). "Vimentin was negative when examined for a possible sarcomatoid metastasis due to a history of osteosarcoma." (PMID 34325712, 2021). "Using dual luciferase assay and RIP experiments, we identified miR-483 as a target of NEAT1, and the exogenous expression of NEAT1 reduced miR-483 expression, subsequently upregulating the expression of N-cadherin, Vimentin and Snail and promoting the EMT in osteosarcoma cells." (PMID 33546665, 2021). "Downregulation of GAS5 in hFOB 1.19 and U2OS osteosarcoma cells enhanced their migration and invasion, along with an upregulated epithelial–mesenchymal transition (EMT), as evidenced by downregulated E-cadherin and upregulated vimentin, ZEB1, and ZEB2." (PMID 34386496, 2021).
osteosarcoma (continued). "Where facilities are available, immunohistochemical demonstration of vimentin with absence of epithelial, neural, muscular and other markers suggest the diagnosis of osteogenic sarcoma." (PMID 17156481, 2006). "Western blotting results indicated that E-cadherin expression was suppressed while vimentin and N-cadherin levels were upregulated in MG-63/Dox cells compared to parental MG-63 cells, suggesting that doxorubicin-resistance is related to EMT promotion in osteosarcoma." (PMID 33762953, 2021). "The inhibitory effects of ML264 on osteosarcoma cells are likely mediated via inhibition of JAK2 and STAT3 phosphorylation, decrease in β‐catenin and Runx2 levels, down‐regulation of cyclin D1, cyclin E1, CDK4, N‐cadherin, vimentin, Snail and MMPs expression, and up‐regulation of E‐cadherin levels." (PMID 32285603, 2020). "Therefore, when considering the expression of vimentin and snail as markers of EMT, FAM83H-mediated expression of vimentin and snail might explain how FAM83H is involved in the invasiveness of osteosarcoma cells." (PMID 31215499, 2019). "Therefore, when considering the roles of FAM83H in the expression of vimentin and snail, FAM83H-mediated EMT, which enhances invasiveness of osteosarcomas, might explain how FAM83H is involved in the progression of osteosarcoma." (PMID 31215499, 2019). "Moreover, the up-regulation of MMP-9, Vimentin and N-cadherin and the downregulation of E-cadherin were observed in Lnc-ZFAS1 overexpressed U2OS cells, and the contrast results were induced by Lnc-ZFAS1 depletion, implying Lnc-ZFAS1’ promotion effect on EMT in osteosarcoma." (PMID 36473367, 2023). "Additionally, in order to explore the underlying molecular mechanism of Lv-shNOB1 suppressing the proliferation and migration of osteosarcoma cells, the expression of several molecules, including fibronectin, vimentin, N-cadherin, E-cadherin and β-catenin was detected (data not shown)." (PMID 24714960, 2014).